RN7SKP264 (RN7SK pseudogene 264)
Gene: Miscellaneous RNA gene on chromosome 9 (86,258,358 to 86,258,646, reverse strand). Ensembl gene ENSG00000223012.
Homologues: Orthologues: chimpanzee 7SK (95% identical), guinea pig 7SK (59% identical), mouse Gm55666 (57% identical). Paralogues in human: RN7SKP273 (74% identical), RN7SKP255 (73% identical), RN7SKP163 (72% identical), RN7SKP243 (72% identical), RN7SKP9 (72% identical), RN7SKP180 (72% identical), RN7SKP176 (72% identical), RN7SKP203 (72% identical), RN7SKP78 (72% identical), RN7SKP211 (71% identical), RN7SKP44 (71% identical), RN7SKP79 (71% identical), and 284 more.